AVP (arginine vasopressin)
Diseases named in the same sentence as AVP in open-access papers (continued):
Sharing a sentence is not in itself a finding about the gene and the disease.
electrolyte disorder (13 papers, 2018 to 2025). "The pathological process is generally exacerbated via the activation of the RAAS and AVP pathways and develops into water and electrolyte disorders." (PMID 41403091, 2025). "It has been suggested that such hyperactivity of AVP neurons may in itself lead to electrolyte disorders in the elderly, but the relationship between the activity of AVP neurons and circulating levels of AVP is poorly understood." (PMID 29494864, 2018).
hypopituitarism (13 papers, 2019 to 2025). A condition of diminution or cessation of secretion of one or more hormones from the anterior pituitary gland. "Hypopituitarism can therefore occur as an isolated pituitary hormone deficiency, but more commonly it occurs in the context of deficiencies in multiple pituitary axes, including the somatotrophic-, corticotrophic-, gonadotrophic-, thyreotrophic axis and arginine vasopressin (AVP) deficiency." (PMID 39215905, 2024).
autism spectrum disorder (12 papers, 2009 to 2023). A spectrum of developmental disorders that includes autism, and Asperger syndrome. "In humans, AVP has been implicated in psychopathology, as variations in the vasopressin V1a receptor (V1aR) gene and AVP serum levels are associated with autism spectrum disorder (ASD)." (PMID 36860367, 2023). "AVPR1B has been associated with autism spectrum disorders and is a receptor involved in the AVP-mediated activation of the hypothalamic-pituitary-adrenal-axis." (PMID 33834688, 2021). "Studies that have compared AVP levels in individuals with autism spectrum disorder (ASD) to typically developing controls have reported mixed results." (PMID 37313445, 2023). "Dysfunction of brain-derived arginine-vasopressin (AVP) systems may be involved in the etiology of autism spectrum disorder (ASD)." (PMID 28258508, 2017). "We therefore hypothesized that AVP signaling deficits may contribute to social impairments in children with autism spectrum disorder (ASD)." (PMID 26200852, 2015). "Oxytocin (OXT) and arginine-vasopressin (AVP) play a key regulatory part in social and affiliative behaviors; two aspects highly compromised in Autism Spectrum Disorder (ASD)." (PMID 29487501, 2018).
lung cancer (12 papers, 2010 to 2025). A malignant neoplasm involving the lung. "Excessive release of AVP relative to the osmotic pressure from the pituitary by excessive stimulation of the pressure receptors in the carotid sinus or from AVP-producing tumors, including lung cancer, causes SIADH." (PMID 34289912, 2021). "SIAD may be due to the tumoral secretion of arginine vasopressin (AVP), which occurs most frequently in lung cancer, or may be induced by drugs (e.g., chemotherapeutics, opioids), nausea, or pain." (PMID 39125971, 2024).
brain injury (11 papers, 2013 to 2025). Acute and chronic (see also brain INJURIES, CHRONIC) injuries to the brain, including the cerebral hemispheres, CEREBELLUM, and brain STEM. "It has been demonstrated that AVP is released as a response to peripheral inflammation and in brain injury AVP secretion also increases." (PMID 31949182, 2020). "Especially in brain trauma, intracerebral AVP is said to exert proinflammatory effects." (PMID 36434506, 2022). "It has been shown that arginine-vasopressin (AVP) released after ischemic brain injury may exacerbate brain edema." (PMID 28854286, 2017).
cerebral edema (11 papers, 2015 to 2025). "Arginine-vasopressin (AVP) induces production of inflammatory molecules after cerebral edema, and it is associated with disruption of the blood-brain barrier (BBB)." (PMID 28865453, 2017). "The possible processes by which serum copeptin is thought to increase in severe acute ischaemic stroke include the presence of cerebral oedema that is contributed to by AVP release." (PMID 38957516, 2024). "Next, we assessed AVP; while AVP is known to play a role in propagating brain neurotoxicity in traumatic brain injury and cerebral edema, increased levels of AVP have also been reported to play a primary role in the regulation of the HPA axis during adaptation to stress." (PMID 34205191, 2021). "Moreover, the symptoms of hyperammonemia, a prerequisite for the development of cerebral edema in HE, become more pronounced in the presence of arginine-vasopressin (AVP, syn." (PMID 29216295, 2017). "Since the AVP response to serum osmolality is intact, patients will have a water diuresis in response to excessive intake and there is therefore no risk of water overload and cerebral edema." (PMID 30587223, 2018).
myocardial infarction (11 papers, 2018 to 2025). Gross necrosis of the myocardium, as a result of interruption of the blood supply to the area, as in coronary thrombosis. "Moreover, experimental studies revealed that, in post-myocardial infarction, cardiac dysfunction is associated with increased cardiac and plasma AVP and Ang II expressions, and that AVP expression is positively correlated with left ventricular end diastolic diameter (LVEDD)." (PMID 29556787, 2018). "During myocardial infarction, the stress hormone arginine vasopressin (AVP), also known as antidiuretic hormone, is released in response to stress and hemodynamic changes." (PMID 40677457, 2025). "Tsc22 is also upregulated in the left ventricle of spontaneously hypertensive rats (SHR), in experimental myocardial infarction models and in models of LVH caused by chronic pressure overload driven by either arginine vasopressin or angiotensin II." (PMID 36388115, 2022). "A myocardial infarction (MI) stimulates VPS, causing the significant activation of vasopressinergic magnocellular neurons in the SON and the elevation of plasma AVP levels." (PMID 36430892, 2022). "Specifically, a decrease of AVP-mediated cAMP accumulation in the thick ascending limb of the loop of Henle and restoration of a normal NKCC2 expression was found in rats with myocardial infarction [344•]." (PMID 29556787, 2018). "This does not preclude the possibility that a massive increase in AVP/copeptin, e.g., during hypovolaemic shock or myocardial infarction, might provide a stimulus for cortisol secretion." (PMID 36359377, 2022).
meningitis (10 papers, 2018 to 2025). A disorder characterized by acute inflammation of the meninges of the brain and/or spinal cord. "Meningitis causing a high fever leads to dehydration, which can trigger secretion of AVP, thus affected patients were usually treated with hydration and antibiotics." (PMID 35984619, 2022). "It is possible that the severity of meningitis is correlated with the AVP secretion levels in SIADH." (PMID 34289912, 2021).
nephrogenic syndrome of inappropriate antidiuresis (10 papers, 2016 to 2025). "Plasma AVP levels are undetectable due to mutations in the V2 vasopressin receptors in the nephrogenic syndrome of inappropriate antidiuresis." (PMID 37700952, 2023). "They described two infants whose clinical and laboratory findings were consistent with SIADH but had undetectable plasma AVP levels because of gain-of-function mutations in the vasopressin V2 receptor (V2R), and coined the term ‘nephrogenic syndrome of inappropriate antidiuresis (NSIAD)’." (PMID 36233678, 2022). "These mutant receptors have increased binding affinity to AVP or are constitutively activated, causing the nephrogenic syndrome of inappropriate antidiuresis (NSIAD)." (PMID 29125546, 2017). "However, a gain-of-function variant of the vasopressin V2R, which causes impaired urinary dilution despite plasma AVP concentrations below the detection limit, has been termed the nephrogenic syndrome of inappropriate antidiuresis (NSIAD)." (PMID 39847311, 2025). "Renal water retention can occur without the stimulation of arginine vasopressin, and spontaneous or drug-induced activation of the vasopressin-2 receptor (V2R) is known to cause nephrogenic syndrome of inappropriate antidiuresis (NSIAD)." (PMID 39202754, 2024). "A mutation in the V2R gene that causes nephrogenic syndrome of inappropriate antidiuresis (NSIAD) leads to constitutively active receptors triggering SIADH-like symptoms without elevated AVP levels." (PMID 26903868, 2016).
autosomal dominant polycystic kidney disease (9 papers, 2015 to 2024). Autosomal dominant form of polycystic kidney disease. "Hyperactivation of the AVP system has been implicated in the progression of autosomal dominant polycystic kidney disease (ADPKD), a genetic disorder characterized by the development of numerous fluid-filled cysts in the kidneys." (PMID 39273390, 2024). "Maintaining hydration sufficient to reduce levels of arginine vasopressin has been hypothesised to slow kidney cyst growth in autosomal dominant polycystic kidney disease (ADPKD)." (PMID 30096903, 2018). "Maintaining fluid intake sufficient to reduce arginine vasopressin (AVP) secretion has been hypothesised to slow kidney cyst growth in autosomal dominant polycystic kidney disease (ADPKD)." (PMID 29358433, 2018).
ischemic stroke (9 papers, 2015 to 2025). A stroke disorder caused by obstruction of blood flow to the brain, due to thrombotic (local blood clot formation) or embolic (due to a blood clot or other material traveling from another site) event. "Previous studies have suggested that AVP plays an important role in regulating the brain volume, electrolyte homeostasis, and microvascular resistance in ischemic stroke." (PMID 40508137, 2025). "Elevated AVP levels in blood plasma were observed in patients with ischemic stroke during the 24 h period." (PMID 36768443, 2023). "Insulin, estrogen, progesterone, testosterone, arginine vasopressin, and thyroid hormone have been reported successively in ischemic stroke, which gradually fills the gap of hormones in the field of ischemic stroke research." (PMID 36569944, 2022). "This review provides an update on understanding AVP involvement in ischemic stroke." (PMID 36768443, 2023). "Patients with ischemic stroke show a significant increase of AVP in plasma and cerebrospinal fluid." (PMID 36768443, 2023). "On the other hand, AVP affects astrocytic functions and regulates the onset of ischemic stroke." (PMID 28865453, 2017). "Ischemic stroke causes breakdown of BBB, and AVP’s actions on V1a receptors may play an important role in BBB integrity." (PMID 26275173, 2015). "Ischemic stroke is often complicated by brain edema, disruption of blood-brain barrier (BBB), and uncontrolled release of arginine-vasopressin (AVP)." (PMID 28854286, 2017).
mood disorder (9 papers, 2012 to 2025). A cognitive disorder a disturbance in which the person's mood is hypothesized to be the main underlying feature. "Zhou and colleagues interpreted the results as suggesting that AVP transport and release is decreased in the SCN of subjects with mood disorders, which results in a buildup of AVP in SCN neurons." (PMID 29230328, 2017). "In spite of a mass of empirical data showing that the OT and AVP systems are perturbed in neurodevelopmental and mood disorders, the mechanisms that lead to disrupted OT and AVP function are currently unclear." (PMID 25741359, 2015). "The adverse effects of mood disorders are often mediated through maternal behavior and recent work has identified arginine vasopressin (AVP) as a key neuropeptide hormone in the expression of maternal behavior in both rats and humans." (PMID 24349762, 2012). "Interestingly, in this mood disorder cohort, the authors also reported decreased levels of AVP mRNA, together indicating a defective neuropeptidergic transport and turnover in subjects with mood disorder." (PMID 40055943, 2025). "Studies have implicated AVP, nitric oxide, and melatonin signaling in the SCN in mood disorders, but it is unknown whether SCN neural activity is altered in MDD or bipolar disorder." (PMID 29230328, 2017). "Using an established rodent model that elicits behavioral and physiological responses similar to human mood disorders, this study tested the effectiveness of chronic AVP infusion as a novel treatment for the adverse effects of exposure to chronic social stress during lactation in rats." (PMID 24349762, 2012). "Considering the suggested contribution of CA2 to episodic memory, this cellular effect of AVP may contribute to the central influence of this neuropeptide in memory and mood disorders." (PMID 23236353, 2012). "Thus, SCN AVP and VIP signaling may be altered in mood disorders." (PMID 29230328, 2017). "Importantly, we demonstrate that selectively reducing AVP expression in the PVN of HW mice mitigates depressive behaviors without affecting social discrimination, suggesting that PVNAVP neurons modulate mood disorders specifically, rather than social behaviors." (PMID 40370500, 2025).
nephrotic syndrome (9 papers, 2014 to 2025). A collection of symptoms that include severe edema, proteinuria, and hypoalbuminemia; it is indicative of renal dysfunction. "In line with this, physiological investigations in children with nephrotic syndrome have revealed elevated levels of AVP." (PMID 26553121, 2015). "The therapeutic effect of AR on nephrotic syndrome (NS) may be demonstrated by reducing the expressions of arginine vasopressin (AVP) mRNA, AVP V2 receptor mRNA, and AVP-dependent aquaporin-2 (AQP2) mRNA, thereby eliminating edema." (PMID 35924053, 2022). "The results showed that the serum levels of cholesterol, triglyceride, TNF-α, and IL-6 in rats with nephrotic syndrome were increased and the gene and protein expressions of AQP2 and AVP were up-regulated in rats with adriamycin injected into caudal vein." (PMID 36678585, 2023).
Abdominal obesity (8 papers, 2014 to 2025). Excessive fat around the stomach and abdomen. "Recently, imbalance in the vasopressin (AVP) system, measured as elevated levels of copeptin (the C-terminal part of the AVP pro-hormone) in plasma, was linked to the development of abdominal obesity and diabetes mellitus (DM)." (PMID 26503846, 2016). "These include central obesity, induced by various environmental factors, secretion of AVP (arginine vasopressin) or its C-terminal fragment (copeptin)." (PMID 29460258, 2018).
cardiac hypertrophy (8 papers, 2006 to 2025). "The activation of the Mst1-Nrf2 pathway has been shown to be protective against oxidative stress and apoptosis in cardiac hypertrophy and arginine vasopressin (AVP)-stressed cardiomyoblasts." (PMID 37760018, 2023). "AVP exerts its effect through 3 types of receptors namely the V1 (vasoconstriction and myocardial hypertrophy), the VIb (release of adrenocorticotropic hormone), and the V2 receptor (water retention in the renal collecting duct)." (PMID 26158609, 2015). "Although our study suggests that the AKT1–SERCA2 cascade exerts important functions in AVP-induced pathological cardiac hypertrophy, there may be some differences with those in vivo." (PMID 32489586, 2020). "Due to the potential effects of AVP on V12 and V2 receptors, these receptors could worsen cardiac function by increasing cardiac preload and afterload which led to increased ventricular wall pressure, dilation, and hypertrophy." (PMID 36157210, 2022). "However, the specific mechanism by which Met alleviates AVP-induced pathological cardiac hypertrophy is still unknown." (PMID 32489586, 2020). "Copeptin is a propeptide fragment of arginine vasopressin (AVP), which mediates vasoconstriction and cardiac hypertrophy." (PMID 31118017, 2019). "Arginine vasopressin (AVP) is released from the hypothalamus in response to changes in arterial pressure and plasma osmolality, and many previous studies have shown that AVP can induce peripheral vasoconstriction and cardiac hypertrophy." (PMID 32489586, 2020).
glucocorticoid deficiency (8 papers, 2010 to 2023). "The glucocorticoid deficiency impairs free water excretion via both arginine vasopressin (AVP)‐dependent and independent mechanisms." (PMID 36518913, 2022). "Lastly, glucocorticoid deficiency also leads to a decrease in the stroke volume and cardiac output, resulting in non‐osmotic stimulation of AVP secretion." (PMID 36518913, 2022). "With glucocorticoid deficiency, the hypotonic suppression of the osmostat for AVP release is impaired." (PMID 28812008, 2017). "This would seem to correlate with reports that patients with glucocorticoid deficiency have increased plasma levels of AVP and a sustained hypersecretion of AVP despite plasma dilution." (PMID 20170523, 2010).
preeclampsia (8 papers, 2013 to 2025). Preeclampsia is a hypertensive disorder of pregnancy that is characterized by new-onset hypertension with proteinuria presenting after 20 weeks of gestation, and depending on mild or severe forms may initially present with severe headache, visual disturbances, and hyperreflexia. "In light of these findings, we posit that the preeclampsia-protective effect of SSRI therapy is associated with decreased peripheral AVP (Graphical Abstract)." (PMID 35984571, 2023). "We and others reported previously that offspring of the arginine vasopressin or ANG II animal models for the study of preeclampsia and maternal hypertension exhibit dysregulation of immune-related genes in the brain." (PMID 40519163, 2025). "AVP secretion (as assayed by circulating copeptin) is a mechanistically interesting link between the serotonergic disorders of depression and preeclampsia." (PMID 35984571, 2023). "In summary, the present study reveals that chronic gestational AVP, modeling preeclampsia, affects the developing brain." (PMID 33510137, 2021). "While preeclampsia is diagnosed only after the 20th week of gestation and AVP administration begins slightly prior to conception in the AVP model, this too supports its translational value." (PMID 33510137, 2021). "One unique mouse model of preeclampsia involves continuous maternal administration of arginine vasopressin (AVP) throughout pregnancy." (PMID 33510137, 2021). "Deficits in behavior and forebrain development in this AVP-based preeclampsia model were distinctly different in males and females, implicating different neurobiological bases." (PMID 33510137, 2021). "The novel findings presented here support the hypothesis that AVP secretion, as measured by copeptin, is modulated by SSRI use in women with depression symptoms, a population that is at increased risk for preeclampsia." (PMID 35984571, 2023). "Despite epidemiological evidence linking selective serotonin reuptake inhibitors (SSRIs) in pregnancy to preeclampsia, serotonin (5-HT) and vasopressin (AVP) secretion mechanisms suggest that SSRIs may attenuate preeclampsia risk." (PMID 35984571, 2023). "We hypothesized that chronic prenatal maternal AVP in mice would recapitulate preeclampsia-like outcomes in children, including altered behavior and neurodevelopment." (PMID 33510137, 2021). "The DMR analyses of HDP and preeclampsia identified a region that was annotated to AVP gene." (PMID 31230546, 2019). "The increased sociability in males in this AVP model may not appear directly analogous to the social deficit of ASD disorder for which preeclampsia exposure is a risk." (PMID 33510137, 2021). "Administration of AVP just prior to conception and chronically throughout gestation in this model thus disrupts maternal physiology in its earliest stages, as many have argued occurs in clinical preeclampsia, and elicits critical, translationally-relevant preeclampsia phenotypes." (PMID 33510137, 2021). "Our results showed hyponatriuria in preeclampsia, rather than the natriuretic effects of progesterone, arginine vasopressin, atrial natriuretic factor, prostaglandins and other factors that may lead to excessive loss of filtered sodium." (PMID 23657513, 2013).
psychosis (8 papers, 2015 to 2025). "Evaluate whether plasma OT and AVP and saliva OT levels differ across sex, genetic subtype, or the presence of psychosis in individuals with PWS." (PMID 37313445, 2023). "On the other hand, we also reported increased expression of AVP and AVPR1A in the placentas of women who underwent a first-episode psychosis during pregnancy." (PMID 37373400, 2023).